RN7SL870P (RNA, 7SL, cytoplasmic 870, pseudogene)
Gene: Miscellaneous RNA gene on chromosome 3 (47,560,229 to 47,560,524, reverse strand). Ensembl gene ENSG00000244732.
Homologues: Orthologues: chimpanzee Metazoa_SRP (98% identical), macaque Metazoa_SRP (88% identical), dog Metazoa_SRP (68% identical). Paralogues in human: RN7SL3 (81% identical), RN7SL1 (80% identical), RN7SL321P (80% identical), RN7SL296P (80% identical), RN7SL2 (79% identical), RN7SL664P (79% identical), RN7SL218P (78% identical), RN7SL230P (78% identical), RN7SL607P (78% identical), RN7SL322P (78% identical), Metazoa_SRP (77% identical), RN7SL413P (77% identical), and 703 more.